VIM (vimentin)
Diseases named in the same sentence as VIM in open-access papers (continued):
Sharing a sentence is not in itself a finding about the gene and the disease.
tumor (continued). "EMT-mediated tumor metastasis is stimulated by transcription factors, such as TWIST1, SNAI1, and ZEB1, known to upregulate vimentin." (PMID 37161053, 2023). "In vitro nerve‐tumor co‐culture results showed that GAL increased the expression of N‐cadherin and Vimentin (mesenchymal biomarkers) while suppressing the expression of E‐cadherin (epithelial biomarker) in SACC cells." (PMID 36039037, 2023). "In contrast, significant correlations were found for FAP, vimentin, CAIX, CD68 and CD44, thus indicating that tumoroids are able to retain the inter-tumor heterogeneity present in the tumor tissues." (PMID 37736770, 2023). "The immunoreactivity of vimentin and α-SMA was analyzed for assessing tumor EMT, signs of malignant tumor growth." (PMID 38110966, 2023). "Single cells co-expressing EpCAM, Vimentin and CD24 were abundant in the stroma surrounding metastatic tumours." (PMID 37975646, 2023). "Catulin GFP + cells marked smaller population of cancer cells with the majority of them co-expressing Vimentin (d’ and e, e’), and the level of Vimentin expression in GFP positive cells, at the tumor invasion front, was much higher than in the tumor center." (PMID 35879327, 2022). "Mural nodules: polygon or spindle and giant tumor cells showed strong positive expression of cytokeratin (CK), epithelial membrane antigen (EMA), and vimentin (VIM), while CD163, S-100, Desmin, CD31, and MyoD1 were negative." (PMID 35836292, 2022). "The expression levels of N-cadherin, Vimentin, Snail, MMP9 and HIF-1α were significantly decreased in the xenograft tumor tissues from mouse model injected with M2 cells treated with OL, when compared with those of the control group." (PMID 36050634, 2022). "It is associated with a decrease in E-cadherin expression and an increase in vimentin, indicating a direct interaction between EMT and tumor progression." (PMID 36499660, 2022). "Vimentin over-expression, a molecular characteristic of EMT, has been reported in cancers and correlated with increased tumor growth, invasion, and poor prognosis." (PMID 35081125, 2022). "As expected, HES1, HEY2, N-cadherin, and Vimentin expression was increased, and E-cadherin expression was decreased in MDA-MB-231 tumor with BEND5 knockdown." (PMID 35844785, 2022). "Further, IHC staining of the xenograft tumor tissue revealed that CD31, vimentin, N-cadherin, and Ki-67 were repressed when FBXW5 was depleted." (PMID 35210431, 2022). "Heparanase, MMP9, vimentin, and VEGF-B protein levels, were studied in both tumor and non-tumor adjacent tissues of all stages from CRC patients." (PMID 36139645, 2022). "Subsequently, these removed tumours were verified by HE staining, and the IHC results showed that increased LIMA1 levels in vivo evidently abolished Ki67 and vimentin expression but facilitated E-cadherin expression." (PMID 36497115, 2022). "This shows high heterogeneity within tumor mass with Catulin-GFP reporter, marking tumor cells with the highest Vimentin expression." (PMID 35879327, 2022). "Immunohistochemically, the tumor cells diffusely expressed S100, alpha-inhibin, neuron-specific enolase (NSE), vimentin and PAX8." (PMID 35220972, 2022). "The results demonstrated that the overexpression of BHLHE41 significantly decreased the levels of N-cadherin, vimentin, and MMP9 and significantly increased the level of E-cadherin in tumor tissue (P < 0.01)." (PMID 35615737, 2022). "Immunohistochemical staining shows that tumor cells are positive for CD10, cyclin D1 and vimentin and variably positive for WT1 and CD56." (PMID 36428715, 2022). "The expression of E-cadherin was found in all tumor tissues before treatment and decreased in patients after EGFR-TKI resistance with the expression of vimentin elevated." (PMID 35646083, 2022). "The migrative cell number decreased in shNK1R-transfected cells, along with the reduced protein level of vimentin, MMP2 and −14, showing the reduced ability of tumor cell metastasis." (PMID 35013118, 2022).
tumor (continued). "Serial sections were used to spatially interrogate antigen expression of vimentin, VCAM-1, CD31, Ki67, nestin, and SOX2 in both tumor cells and the adjacent stroma, specifically at the tumor core, tumor rim, and contralateral striatum." (PMID 35312755, 2022). "Next, we used three mesenchymal biomarkers (N-cadherin, vimentin, and Twist) to evaluate the EMT status of these tumor cells." (PMID 35897747, 2022). "With the aim of understanding some of the mechanistic changes brought about by vimentin expression in tumor-derived human breast epithelial cells null for vimentin expression, MCF7 cell lines with inducible vimentin expression were established." (PMID 36200046, 2022). "In a hormone-sensitive human tumor cell line, it was also shown that DHT enhanced the expression of vimentin." (PMID 36206048, 2022). "The WB showed that, compared to the control group, tumor tissues with stable overexpression of MIR99AHG had decreased expression of the TGF-β1, Vimentin, and ACTA2 and COL1A1." (PMID 36138468, 2022). "In this situation, miR-204 acts as a tumor suppressor, while SIRT1 downregulation induces a MET phenotype, with a decrease in Vimentin and an increase in E-cadherin expression." (PMID 35745656, 2022). "Moreover, based on the expression of EMT hallmark genes including SNAI2, N-cadherin, Vimentin, ZEB1, ZEB2, SNAI1, Fibronectin, TWIST1 and E-cadherin, we found that patients with high risk score distinctly exhibited a mesenchymal phenotype, suggesting a higher tumor malignancy." (PMID 36505846, 2022). "The CXCR4+ vimentin+ cells were observed in the tumor budding in the primary tumor margin, demonstrating that the CXCR4+ cells previously identified by IHC were indeed human cancer cells (vimentin+)." (PMID 35456719, 2022). "Consistent with our results, it has been shown in vitro that exposure to the DBP metabolite monobutyl phthalate (MBP) upregulated vimentin expression in the murine Y1 and MLTC-1 tumour cell lines." (PMID 35955852, 2022). "Conversely, CXCR4 overexpression strikingly counteracted the effect of PTX on decreasing Akt phosphorylation and reductions in N-cadherin, vimentin, snail, CD44, CD133, and NANOG protein expression in SKOV3 tumor tissues (*P<0.05)." (PMID 35681259, 2022). "Immunohistochemically, tumor cells are positive for CD10, cyclin D1 and vimentin and variably positive for WT1, FOXL2, and SF1." (PMID 36428715, 2022). "In all, our data demonstrate that vimentin, like VEGF, (i) reduces VE-cadherin expression, cell-cell interactions and vascular integrity, (ii) supports tumor angiogenesis, and (iii) hampers antitumor immunity." (PMID 35606362, 2022). "In this study, we demonstrated that PTEN loss promotes pNET invasion and migration through the upregulation of VEGFR3 phosphorylation, ERK phosphorylation, and the expression of the EMT molecules vimentin and SLUG in tumor cells." (PMID 36336681, 2022). "Citrullinated GRP78 189-208 peptide was detected with linearity value (R2) of greater than 0.90 and compared to detection of two vimentin and one alpha-enolase peptides known to be CD4 T cell targets in the same tumour model." (PMID 36544781, 2022). "Immunohistochemical analysis of 227 oral tumors suggested a significant correlation of vimentin expression with various prognostic factors of OSCC, such as the tumor size, clinical stage, regional lymph node metastasis, local recurrence, and poor survival." (PMID 35207438, 2022). "To this end, we compared protein levels of E-Cadherin, Vimentin, N-Cadherin, ZEB1 and SLUG in paired normal mucosa/tumor samples derived from L5, L6 and L7 patients." (PMID 35837106, 2022).
tumor (continued). "We found that the expression of epithelial marker E-cadherin was downregulated, while the expression of mesenchymal markers, including ZEB-1, Vimentin, Slug and α-SMA, were upregulated, indicating the enhanced EMT in tumor issuses pretreated with ISO." (PMID 35517411, 2022). "A core needle biopsy showed a small, round blue cell neoplasm, (suggestive of a primitive neuroectodermal) stained positive for CD99 and vimentin stain." (PMID 36193025, 2022). "Immunohistochemical analysis of the tumour tissues showed changes in the protein expression of MMP9, vimentin, Bax, Bcl‐2, p‐p65, CDK9, MMP2, N‐cadherin and MIF." (PMID 35060345, 2022). "The stimulation of NFs and CAFs with these media induced an increase in the expression of type I collagen, vimentin and FSP1, which demonstrates the acquisition of a more secretory phenotype, characteristic of the tumor stroma." (PMID 35743206, 2022). "Our previous findings indicate that low MCPIP1 expression induces the expression of Snail1 and vimentin and increases the expression and phosphorylation of c-Met, whereas increased MCPIP1 suppresses tumor growth and inhibits the metastatic process." (PMID 36138026, 2022). "Tumor cells were always positive for β-catenin, CD10, CD56, cyclin-D1, progesterone receptor (PR), and vimentin by immunohistochemistry." (PMID 35204541, 2022). "The differential analysis also confirmed the high expression of CD74, HLA-DRA, C7, CCL12, and CCR3 in CAFs from P-LN but lower expression of VIM, APOD, MMP11, TAGLN, and CDKN2A compared with that in the primary tumor." (PMID 36569924, 2022). "Low E-cadherin expression and high vimentin expression are markers of epithelial-mesenchymal transition (EMT), which is often related to tumor invasion and metastasis." (PMID 35619108, 2022). "Immunohistochemically, the neoplasm cells were diffuse positive for PAX8, AMACR, AE1/AE3, and Vimentin." (PMID 36550861, 2022). "In CTH cells, the co-existence of vimentin and E-cadherin resembled a partial EMT hence ensuring their plasticity while preserving the same tumor-propagating potential." (PMID 36077806, 2022). "Vimentin and VEGF-B expression levels were studied according to the tumor stage (I, II, III, and IV) to link them to relapse-free survival of CRC patients." (PMID 36139645, 2022). "Vimentin at ITF and tumor sites has been shown to be strongly correlated to aggressive phenotype contributing to poor prognosis." (PMID 35498535, 2022). "By IHC, the tumor cells were diffusely positive for TLE-1 and vimentin and focally positive for epithelial membrane antigen, AE1/3, Cam5.2, SATB2, and CD34 (all in less than 10% tumor cells)." (PMID 35125107, 2022). "Immunohistochemically, the tumor cells were positive for syn, CR, CgA, and vasopressin and were focally positive for NeuN, TTF-1, NF, CK8, vimentin, and S100 proteins." (PMID 35663322, 2022). "Positive CTCs for vimentin(CTCvim) were detected in 76 of 100 patients with PDAC, using a microfluidic assay.CTCvim counts were correlated with changes in tumor burden for patients undergoingresection." (PMID 35107490, 2022). "αPD‐L1 enhances the protein expression of E‐cadherin, and weakens the protein expression of vimentin, VEGF and CD44 in tumour tissues." (PMID 36372977, 2022). "Immunohistochemically, the tumor cells were positive for synaptophysin, chromogranin A, and calretinin and were focally positive for NeuN, TTF1, NF, CK8, vimentin, and S100 proteins." (PMID 35663322, 2022). "Immunohistochemistry staining (magnification, ×400) showed that the tumor cells were positive for STAT6, CD34, Ki67 (10%), CD99, Bcl2, and Vimentin." (PMID 36386546, 2022).
tumor (continued). "Downregulation or deletion of E-cadherin expression leads to an increase in cell activities, while vimentin is an intermediate filament protein existing in mesenchymal cells, and its increased expression represents the occurrence of EMT in tumor cells." (PMID 36003306, 2022). "In accordance to that, we found an increase of VIMENTIN and SNAIL gene family expression in tumor cell lines after co-culture with platelets." (PMID 35265204, 2022). "We further assessed the role of hnRNPC and IQGAP3 in tumor progression by tracing the expression of key epithelial-mesenchymal transition (EMT) markers such as E-cadherin, N-cadherin, and vimentin." (PMID 35355828, 2022). "In the late stages of cancer, TGF-β signaling increases the expression of mesenchymal markers N-cadherin and vimentin and downregulates the epithelial marker E-cadherin to promote EMT in tumor cells by mediating SMAD." (PMID 35563845, 2022). "Mechanistic studies using tumor tissues showed that artemisinin decreased mRNA levels of c-Myc, cyclin D1, PCNA, N-cadherin, Vimentin and Snail, but increased mRNA levels of E-cadherin." (PMID 35805049, 2022). "The loss of E-Cadherin protein was thought to be the start of EMT, whereas the gain of Vimentin and SNAIL gave tumor cells increased migratory ability." (PMID 36329699, 2022). "In the process of EMT, tumor cells either lack cell junction proteins (such as E-CAD, and ZO1) or increase mesenchymal cell marker proteins (such as N-cad, Vimentin, and Snail) that promote tumor cell metastasis." (PMID 35518787, 2022). "Immunohistochemistry showed that the tumor cells were diffusely positive for TLE-1 and vimentin and focally positive for epithelial membrane antigen, AE1/3, Cam5.2, SATB2, and CD34 (all in less than 10% tumor cells)." (PMID 35125107, 2022). "Immunohistochemically, the tumor cells were positive for CD117, vimentin, CD56 and NSE and focally expressed desmin; the cells were negative for myogenin, S-100, SYN, INSM1, CD34, STAT6, INI-1, Brachyury, ERG, TLE1, AE1/AE3, WT-1, CD99 and SMA." (PMID 35488288, 2022). "For instance, in one of the models, a large panCK+ tumor cell cluster is visible inside a blood vessel that is positive for vWF, CD31 and vimentin." (PMID 35121992, 2022). "We added cell line metadata including lineage/tumor type, as well as a feature describing EMT state based on the ratio of CDH1 to VIM expression (see “Methods”)." (PMID 35768873, 2022). "Immunohistochemical staining results revealed that subcutaneous tumor tissue constructed by LAMC1 knockout cell line had up-regulated expression of E-cadherin, down-regulated vimentin and Ki67 expression." (PMID 35541892, 2022). "Immunostaining was performed to assess both proliferative/stem cell (Nestin, Sox2, Ki67, Vimentin, SSEA1, CD133) and quiescent (Cd9 and Gfap) markers within the tumours." (PMID 36420140, 2022). "The expression of FAP, α-SMA, and Vimentin was more strongly correlated with NFYB, and these markers were closely related to tumor invasion and metastasis." (PMID 36152055, 2022). "A study has also implicated the potential to target the cell surface domains of vimentin expressed concomitantly along with the stem cell markers CD44 and CD133 in the tumor-initiating metastatic pancreatic cancer cells derived from lymph nodes." (PMID 35207438, 2022). "Since abnormal activation of EMT is an important biological process in tumor progression, we examined the EMT-related markers ZEB1, E-cadherin, N-cadherin and Vimentin in GC cells." (PMID 35295342, 2022). "Immunohistochemistry staining (magnification, ×400) showed that the tumor cells were positive for CD34, STAT6, Ki67 (8%), CD99, and Vimentin." (PMID 36386546, 2022). "According to our findings, the overexpression of FAM107A elevated E-cadherin expression, reduced N-cadherin and vimentin expression, and interfered with EMT in tumor cells." (PMID 36010909, 2022).
tumor (continued). "Based on tumor-intrinsic features and characteristics of microenvironment in SCLC, we analyzed the CD8+ TIL score and tumor vimentin expression." (PMID 36428693, 2022). "The results revealed that the expression of E-cadherin was downregulated, and N-cadherin, vimentin, Cyclin D1, and pERK1/2 were upregulated in SUN5-OE tumor tissues (p < 0.05), which is consistent with in vitro results." (PMID 36358787, 2022). "Vimentin expression is affected by the downregulation of ZEB1, in turn constraining tumor migration." (PMID 36547923, 2022). "After the xenograft tumour was established in mice, the tumour volume was determined and the expressions of METTL3, miR‐589‐5p, MMP‐2, TIMP‐2, E‐cadherin, N‐cadherin and Vimentin in tumour tissue were detected by RT‐qPCR and Western blotting." (PMID 35348293, 2022). "In histology, tumor tissues were observed by HE staining, besides, MSMO1 and E-cadherin expression were decreased but β-catenin, Vimentin, p-PI3K (Tyr458) and p-AKT (Ser473) expression were increased in Tumor was further confirmed by IHC." (PMID 36046654, 2022). "We investigated the expression of N-cadherin, E-cadherin, vimentin, and MMP9, and found that the epithelial characteristics of tumor cells in the 3D bioprinted environment were decreased, whereas the mesenchymal characteristics increased." (PMID 35983036, 2022). "Data gathered demonstrated that the SMR peptide interacts with Mortalin and Vimentin to inhibit pro-EMT exosome release and induce EMT tumor suppressor protein expression." (PMID 35915218, 2022). "Immunohistochemistry showed that tumor cells consistently and diffusely expressed CD99, and expressed Vimentin, Syn and NSE to varying degrees, while CgA a.nd S-100 were often negative." (PMID 36626543, 2022). "ccRCC 2D cultures (from Grade 2 and 3 tumours) were also established in serum-supplemented DMEM, with over 90% of cells expressing cytokeratin, vimentin and CD13, and over 60% of cells positive for carbonic anhydrase IX (CA9), a marker specific for ccRCC." (PMID 35102500, 2022). "CAF-derived EVs can also inhibit translation of tumor-suppressor genes (e.g., RSU-1, Ras suppressor 1 and STAG2, stromal antigen 2) and promote EMT via increased expression of vimentin and β2-M." (PMID 36671452, 2022). "Next, to validate the presence of SCLC-M subtype in SCLC tumors, we evaluate the expression of vimentin and the CD8+ TIL score in the SCLC tumor samples." (PMID 36428693, 2022). "Most primary tumor cells maintained the expression of the epithelial markers EpCAM and ERα in our xenograft model while expressing ZEB1 and vimentin." (PMID 35440541, 2022). "Next, a wound-healing assay and mesenchymal biomarkers (N-cadherin, vimentin, and Twist) were used to detect the cell migration ability and epithelial–mesenchymal transition (EMT) status of tumor cells." (PMID 35897747, 2022). "While not significant, higher levels of the stem cell markers Nestin, Vimentin and SSEA1 were also seen in the Lrig1 KO tumours." (PMID 36420140, 2022). "As important markers in the tumor EMT process, E-cadherin, ZO-1, Claudin-1 decreased, N-cadherin and Vimentin increased in expression." (PMID 35509688, 2022). "In tumor samples from bladder tissue (n = 5), the expression of AE1/AE3 antigens, and vimentin were found in all of the investigated samples." (PMID 35563359, 2022). "On the other hand, the most supportive were CAFs derived from the ME mRNA subtype of HNSCC tumour mass, characterised by high expression of EMT markers αSMA, vimentin, and desmin and low gene expression of the TP63." (PMID 35565415, 2022). "Stromal fibroblasts in tumor and normal areas were distinguished by staining with antibodies to α-SMA and Vimentin, respectively." (PMID 35948548, 2022).